TNFRSF11A (TNF receptor superfamily member 11a)
Description:
Receptor for TNFSF11/RANKL/TRANCE/OPGL; essential for RANKL-mediated osteoclastogenesis. Its interaction with EEIG1 promotes osteoclastogenesis via facilitating the transcription of NFATC1 and activation of PLCG2 (By similarity). Involved in the regulation of interactions between T-cells and dendritic cells (By similarity).
Synonyms: ODFR; CD265; RANK; FEO; TRANCE-R; LOH18CR1; OFE; OPTB7; OSTS; PDB2; TRANCER
Tractability: Antibody: UniProt places it where antibodies can reach, with high confidence; its Gene Ontology location is reachable by antibodies, with high confidence; UniProt predicts a signal peptide or a membrane-spanning region; the Human Protein Atlas places it where antibodies can reach.
Safety:
Unwanted effects reported when the protein is acted on. In parentheses: how it was acted on, where the effect was seen, and who reports it.
urticaria and Angioedema (source: ClinPGx)
Gene: Protein-coding gene on chromosome 18 (62,325,269 to 62,391,288, forward strand). Ensembl gene ENSG00000141655.
Subcellular location: Cell membrane (Isoform 1); Membrane raft; Cell membrane (Isoform RANK-e5a)
Subcellular location (Human Protein Atlas): Plasma membrane; Cytosol
Pathways (Reactome):
Immune System: TNF receptor superfamily (TNFSF) members mediating non-canonical NF-kB pathway; TNFR2 non-canonical NF-kB pathway
Gene Ontology:
Molecular function: cytokine binding; protein binding; transmembrane signaling receptor activity; signaling receptor activity; tumor necrosis factor receptor activity
Biological process: adaptive immune response; osteoclast differentiation; positive regulation of canonical NF-kappaB signal transduction; positive regulation of ERK1 and ERK2 cascade; positive regulation of JNK cascade; positive regulation of non-canonical NF-kappaB signal transduction; tumor necrosis factor-mediated signaling pathway; cell-cell signaling; circadian temperature homeostasis; lymph node development; monocyte chemotaxis; multinuclear osteoclast differentiation; ossification; positive regulation of bone resorption; positive regulation of cell population proliferation; positive regulation of fever generation by positive regulation of prostaglandin secretion; positive regulation of osteoclast differentiation; response to interleukin-1; response to lipopolysaccharide; response to tumor necrosis factor; signal transduction; cellular response to zinc ion starvation; immune system process; response to ethanol; response to insulin; and 1 more
Cellular component: external side of plasma membrane; plasma membrane; membrane raft; cell surface; membrane
Genetic constraint (gnomAD): Loss-of-function variants: 34 observed, 51.49 expected, observed/expected ratio (o/e) 0.66, 90% interval 0.5 to 0.88. The upper end of that interval is the gene's LOEUF score, 0.88, which puts it in group 3 of 6, group 1 being the genes least tolerant of losing a copy. Missense variants: 709 observed, 730.19 expected, observed/expected ratio (o/e) 0.97, 90% interval 0.91 to 1.03. Synonymous variants: 295 observed, 286.66 expected, observed/expected ratio (o/e) 1.03, 90% interval 0.94 to 1.13.
Homologues: Orthologues: chimpanzee TNFRSF11A (98% identical), macaque TNFRSF11A (94% identical), pig TNFRSF11A (73% identical), rat Tnfrsf11a (69% identical), mouse Tnfrsf11a (68% identical), dog TNFRSF11A (67% identical), guinea pig TNFRSF11A (59% identical), tropical clawed frog tnfrsf11a (31% identical), zebrafish tnfrsf11a (24% identical), zebrafish tnfrsf1b (14% identical), zebrafish cd40 (11% identical), zebrafish hdr (8% identical), and 1 more. Paralogues in human: TNFRSF21 (14% identical), TNFRSF1B (14% identical), LTBR (13% identical), CD40 (12% identical), TNFRSF11B (12% identical), NGFR (11% identical), TNFRSF8 (11% identical), TNFRSF1A (10% identical), TNFRSF25 (10% identical), TNFRSF10B (10% identical), TNFRSF4 (10% identical), TNFRSF14 (9% identical), and 9 more.
Diseases named in the same sentence as TNFRSF11A in open-access papers:
TNFRSF11A is named in the same sentence as 304 diseases in open-access papers, as found by Europe PMC text mining. Sharing a sentence is not in itself a finding about the gene and the disease. The quoted sentences say what the papers report.
osteoporosis (217 papers, 2009 to 2026). A condition of reduced bone mass, with decreased cortical thickness and a decrease in the number and size of the trabeculae of cancellous bone (but normal chemical composition), resulting in increased fracture incidence. "Genetic analysis strongly supported a novel mutation of TNFRSF11A gene which caused osteoporosis." (PMID 34049530, 2021). "Several large GWAS have investigated the genetics of osteoporosis, revealing BMD-associated genes, including ESR1, LRP4, ITGA1, LRP5, SOST, SPP1, TNFRSF11A (RANK), TNFRSF11 (RANKL), and TNFRSF11B (OPG)." (PMID 39769358, 2024). "In the past two decades, it has been well demonstrated that RANKL (also known as TNFSF11) binding to its receptor RANK (also known as TNFRSF11A) drives osteoclast development and it is considered a crucial target protein for osteoporosis treatments." (PMID 33406741, 2021). "Furthermore, CTSK, CSF1, TNFSF11, CTNNB1, TNFRSF11A, and TNF may be the most promising osteoporosis markers." (PMID 37893075, 2023).
breast cancer (171 papers, 2005 to 2026). A primary or metastatic malignant neoplasm involving the breast. "In breast cancers, expression of PR-A transcribes genes involved in cell proliferation and metastatic processes, of particular interest is TNFRSF11A, which encodes for the receptor of RANKL." (PMID 32867363, 2020). "While wt TNFRSF11A expression was detected in all breast cancer cell lines tested, the TNFRSF11A_Δ7,8,9 variant was observed only in MCF10A, T47D, MCF-7 and MDA-MB-468 cell lines when conventional PCR and gel electrophoresis were employed." (PMID 22824341, 2012). "Thus, common variations in TNFRSF11A modify the risk of developing breast cancer in BRCA1-mutation carriers, data that should be replicated in additional and larger datasets." (PMID 27881737, 2016). "In addition, we found two SNPs in TNFRSF11A significantly associated (P < 0.05) with breast cancer risk in BRCA2 mutation carriers." (PMID 27241552, 2016). "There is also the intriguing possibility that the novel RANK variants, identified in this study, and especially TNFRSF11A_Δ7,8,9 have roles in the regulation of mammary stem cell and tumor-initiating cell (mammary cancer stem cells) expansion and renewal capacity, through the NF-kB machinery." (PMID 22824341, 2012). "In addition, the absence of TNFRSF11A_Δ7,8,9 variant from normal breast in conjunction with the observed expression of this transcript in MDA-MB-468 human breast cancer cell line prompted us to further focus on the possible roles of the TNFRSF11A variants in breast cancer." (PMID 22824341, 2012). "It has been known that TNFRSF11A is related to glioma and breast cancer in existing studies, but its relationship with lung cancer is still unclear." (PMID 35437508, 2022). "Furthermore, authors identified six single-nucleotide polymorphisms in the locus encoding for human RANK (TNFRSF11A), that are significantly associated with breast cancer risk in a wide series of BRCA1 mutation carriers." (PMID 30621730, 2019). "Similarly, the level of Tnfsf11 and Tnfrsf11a encoding respectively for the secreted factor RANKL and its receptor, RANK, involved in the oncogenesis of Brca1 mutation-driven breast cancer, was not altered in the absence of Itgα6." (PMID 38835038, 2024).
osteopetrosis (51 papers, 2012 to 2026). Osteopetrosis, also known as marble bone disease, is a descriptive term that refers to a group of rare, heritable disorders of the skeleton characterized by increased bone density on radiographs. "AR RANK deficiency has been reported in 23 patients with osteopetrosis from 14 kindreds homozygous or compound heterozygous for 17 variants of the TNFRSF11A gene." (PMID 41608125, 2025). "In osteopetrosis with osteoclast deficiency, osteoclastdifferentiation is impaired due to mutations in the TNFSF11and TNFRSF11A genes encoding RANKL and its receptorRANK, respectively, or in the CSF1R gene encoding M- CSF." (PMID 37465191, 2023). "Osteopetroses with developmental defects of osteoclasts (osteoclast-poor osteopetrosis) are more rare, secondary to diseases caused by mutations in TNFRSF11A or TNFSF11, encoding RANK and RANKL, respectively." (PMID 33081155, 2020). "In fact, we have recently reported that mutations in the TNFRSF11A gene lead to osteoclast-poor osteopetrosis associated with hypogammaglobulinemia." (PMID 22271396, 2012). "HSCT is also used to treat genetic abnormalities in CLCN7, TCIRG1, SNX10, and TNFRSF11A leading to osteopetrosis." (PMID 33350578, 2021). "Mice deficient in Tnfrsf11a (the gene encoding RANK) have impaired osteoclastogenesis and display severe osteopetrosis." (PMID 31379855, 2019). "The discovery of truncating mutations of TNFRSF11A (W434X and G280X that lack the PLAD) as the cause of rare cases of osteoclast-poor osteopetrosis offered the opportunity for functional study of this region." (PMID 24859969, 2014). "In order to elucidate the role of such an osteopetrosis in the Msx2−/− mouse dental phenotype, a bone resorption rescue was performed by mating Msx2−/− mice with a transgenic mouse line overexpressing Rank (Tnfrsf11a)." (PMID 24278237, 2013). "Deletion of the genes coding for either RANK or RANKL (Tnfrsf11a and Tnfsf11, respectively), blocks OCL production and leads to severe osteopetrosis in mice and in humans, indicating that RANK-RANKL signaling is critical for osteoclastogenesis." (PMID 33912557, 2021). "Our findings suggest genotype-phenotype relationship in TNFRSF11A-associated OPTB7 and DOS remains unclear, and that the deficiency of TNFRSF11A functions might cause DOS, rather than osteopetrosis." (PMID 35812760, 2022).
rheumatoid arthritis (36 papers, 2007 to 2025). A chronic, systemic autoimmune disorder characterized by inflammation in the synovial membranes and articular surfaces. "For rheumatoid arthritis, an intronic variant (rs7237982) in the TNFRSF11A (RANK) gene was prioritized by GenoBoost, with the dominant mode as the inferred mode of inheritance." (PMID 38811555, 2024).
osteosarcoma (29 papers, 2010 to 2025). A usually aggressive malignant bone-forming mesenchymal neoplasm, predominantly affecting adolescents and young adults. "This region excludes previously identified candidate genes including TNFRSF11A, which encodes RANK, and deleted in colorectal cancer (DCC), which nonetheless is frequently reduced in expression in osteosarcoma." (PMID 22685381, 2012).
breast tumors (21 papers, 2012 to 2023). "TNFRSF11A or RANK expression in breast tumours has been found predominately in those tumours with a high grade and proliferation index; it has also received attention as a possible therapeutic agent." (PMID 29188362, 2018).
atherosclerosis (16 papers, 2013 to 2025). A disease characterized by the build-up of fatty material and calcium deposition in the arterial wall resulting in partial or complete occlusion of the arterial lumen. "TNFRSF11A has not been investigated as biomarker in association with progression of atherosclerosis in PAD or the occurrence of cardiovascular events." (PMID 36319844, 2022). "As with TNFRSF11A, Gal-9 has not been investigated as biomarker in association with progression of atherosclerosis in PAD or the occurrence of cardiovascular events." (PMID 36319844, 2022).
lung carcinoma (14 papers, 2014 to 2026). "Among these, AP1S1 and TNFRSF11A exhibited significantly higher expression in lung cancer tissues than in normal tissues." (PMID 41551936, 2026). "The TNFSF11/TNFRSF11A pathway regulates the activation of osteoclasts and induces the migration of tumor cells, notably in breast and lung cancer." (PMID 34504794, 2021). "The remaining six genes (IGKV4‐1, IGKV6D‐41, TNFRSF11A, INHA, IL11 and SCH3) have not been reported in the literature and may be used as potential biomarkers for lung cancer research." (PMID 32686362, 2020).
Insulin resistance (10 papers, 2015 to 2025). Increased resistance towards insulin, that is, diminished effectiveness of insulin in reducing blood glucose levels. "In the liver, it was found that hepatocyte-specific knockout of TNFRSF11A protected against insulin resistance in mice." (PMID 31911667, 2020).
Paget disease (8 papers, 2007 to 2026). A malignant neoplasm composed of large cells with large nuclei, prominent nucleoli, and abundant pale cytoplasm (Paget cells). "Other genes associated with risk of Paget’s disease include TNFRSF11A (encoding RANK) and TNFRSF11B (encoding OPG)." (PMID 36292765, 2022). "Paget’s disease involves a number of genetic factors including the TNFRSF11A and TNFRSF11B genes which encode for RANK and osteoprotegerin (OPG), respectively." (PMID 34068971, 2021). "Two genes involved in bone formation, SQSTM1 and TNFRSF11A, have been shown to cause Paget's disease." (PMID 21619704, 2011). "SNPs located near TNFSF11, TNFRSF11A, and TNFRSF11B have been reported to be closely associated with Paget's disease, osteoporotic fractures, cardiovascular diseases, ankylosing spondylitis, and breast, and esophageal cancers." (PMID 34660648, 2021).
cervical cancer (7 papers, 2013 to 2022). A primary or metastatic malignant neoplasm involving the cervix. "Together with the stem cell marker KLF5, TNFRSF11A induces cancer cell proliferation, migration and invasiveness in cervical cancer." (PMID 36230614, 2022). "The most highly upregulated gene was TNFRSF11A, which has been reported to promote cervical cancer cell migration, invasiveness and proliferation." (PMID 33323552, 2020). "Our results demonstrate that KLF5 and TNFRSF11a promote cervical cancer cell proliferation, migration and invasiveness." (PMID 29146991, 2017). "miR-3150b-3p directly targets TNFRSF11a to inactivate the p38 MAPK signaling pathway and thus inhibits proliferation and metastasis of cervical cancer (Yu, Wang & Li, 2020)." (PMID 34707942, 2021).
COVID-19 (7 papers, 2020 to 2025). A disease caused by infection with severe acute respiratory syndrome coronavirus 2. "Interestingly, we found early levels of TRAIL-R2, TNFRSF11A, and CTRC to be statistically elevated in subjects who would die from COVID-19 complications." (PMID 40424310, 2025).
colorectal cancer (5 papers, 2012 to 2024). A primary or metastatic malignant neoplasm that affects the colon or rectum. "Alternatively, reduced TNFRSF11A mRNA expression may be associated with a specific molecular subtype(s) of colorectal cancer." (PMID 30858927, 2019). "Future larger studies are required to confirm the link between GFI1 and TNFRSF11A and patient outcome, and to determine the role of these genes in colorectal cancer development." (PMID 30858927, 2019). "The role of TNFRSF11A in colorectal cancer tumorigenesis remains to be elucidated." (PMID 30858927, 2019). "There are limited studies reporting TNFRSF11A mRNA expression in colorectal cancer cases." (PMID 30858927, 2019). "Two candidate gene markers (GFI1 and TNFRSF11A) assessed in this study were identified from a previous study led by the The Cancer Genome Atlas (TCGA) Network, and analysis was performed on 112 consecutively collected, archival FFPE colorectal cancer tumour samples." (PMID 30858927, 2019).
familial expansile osteolysis (5 papers, 2019 to 2022). "Dominant gain of function mutations in TNFRSF11A cause familial expansile osteolysis [FEO; MIM: 174810], leading to permanent activation of RANK." (PMID 33435159, 2021). "The TNFRSF11A gene was first implicated in the pathogenesis of PDB through linkage studies followed by positional cloning in familial expansile osteolysis (FEO) and early-onset familial Paget’s disease which identified mutations affecting the first exon of RANK as the cause of both disorders." (PMID 33988819, 2021). "Mutations in the TNFRSF11A gene, which encodes for RANK, were the first to be associated with isolated PDB cases and other, so called, PDB-like disorders, such as familial expansile osteolysis (FEO) and expansile skeletal hyperphosphatasia (ESH)." (PMID 36035996, 2022).
viral infection (5 papers, 2017 to 2021). "We generated mice with targeted deletion of RANK (Tnfrsf11a) in DCs and demonstrate that RANK signaling is redundant for priming naive CD8 T cells but is specifically required for activation of mCTLs in response to viral infection." (PMID 29186688, 2017).
metastatic disease (4 papers, 2018 to 2024). "Our RNAscope® data also showed good agreement with the TCGA study for reduced expression of TNFRSF11A and tumour features consistent with poor prognosis, including high nodal stage and metastatic disease." (PMID 30858927, 2019).
osteomyelitis (4 papers, 2019 to 2025). An acute or chronic inflammation of the bone and its structures due to infection with pyogenic bacteria. "We next investigated the clinical significance of PCD pathways by correlating their GSVA scores with representative inflammatory biomarkers of osteomyelitis, including IL6R, MMP8, TNFRSF11A, IL17RB, TNFSF14, and TGFBR1." (PMID 41050653, 2025).
gestational diabetes (3 papers, 2022 to 2024). Carbohydrate intolerance first diagnosed during pregnancy. "Thymic deletion of the Tnfrsf11a gene (encodes RANK, the receptor for RANKL) caused the reduced accumulation of natural regulatory T (Treg) cells in the placenta and visceral adipose tissue, resulting in miscarriages and gestational diabetes." (PMID 39060500, 2024).
psoriasis (3 papers, 2013 to 2015). An autoimmune condition characterized by red, well-delineated plaques with silvery scales that are usually on the extensor surfaces and scalp. "Other cytokines and receptors with low expression levels and consistently minimal or no changes in psoriasis (IL13, TNFRSF11A, TNFRSF11B, and TNFSF11) showed similar results across all three platforms." (PMID 23308107, 2013).
B cell lymphomas (2 papers, 2021 to 2022). "TNFRSF11A expression in the canine primary B-cell lymphoma samples was also shown to be underexpressed compared to non-neoplastic primary material." (PMID 36230614, 2022).
diffuse large B-cell lymphoma (2 papers, 2024 to 2025). "Recurrent mutations in the RANK encoding gene TNFRSF11A, specifically RANKK240E, found in diffuse large B-cell lymphoma, lead to significant expansion in the B1-cell subset, innate-like, self-renewing B lymphocytes in mice." (PMID 39198400, 2024).
injury (2 papers, 2025 to 2026). Damage inflicted on the body as the direct or indirect result of an external force, with or without disruption of structural continuity. "Tnfrsf11a expression was highest in most mature Mφ and kidney Mφ, highlighting Tnfrsf11a induction during kidney injury." (PMID 40834429, 2025).
myasthenia gravis (2 papers, 2021 to 2023). Myasthenia gravis (MG) is a rare, clinically heterogeneous, autoimmune disorder of the neuromuscular junction characterized by fatigable weakness of voluntary muscles. "In addition, single-nucleotide polymorphisms in either the TNFRSF11A locus (encoding RANK) or the TNFSF11 locus (encoding RANKL) are associated with the autoimmune syndromes myasthenia gravis and autoimmune vitiligo, respectively." (PMID 33075129, 2021).
osteosclerosis (2 papers, 2019 to 2022). Abnormally high bone density. "He had unique metadiaphyseal splaying and osteosclerosis, vertebral end‐plate osteosclerosis, and cortical thinning of long bones but no mutation was detected of SLC29A3, TNFRSF11A, TCIRG1, LRRK1, or CSF1R associated with DSS." (PMID 35991533, 2022).